TFF1 (trefoil factor 1)
Diseases named in the same sentence as TFF1 in open-access papers (continued):
Sharing a sentence is not in itself a finding about the gene and the disease.
gastric polyps (1 paper, 2021). "Most gastric polyps (GPs) displayed immunoreactivity for TFF1 in >75% of the epithelial component." (PMID 34679875, 2021).
gastroenteritis (1 paper, 2022). An inflammatory disorder that affects the upper and lower gastrointestinal tract. "The specific responses of TFF1 hyper-expression have been revealed by Ren and Soutto, who found pathologically increased TFF1 expression in gastroenteritis and gastrointestinal ulcers." (PMID 35693767, 2022).
head and neck cancer (1 paper, 2017). A primary or metastatic malignant neoplasm affecting the head and neck. "However, based on so few studies, we cannot come to a conclusion on the role of TFF proteins, specifically TFF1, in head and neck cancer." (PMID 29296124, 2017). "Furthermore, very few studies have evaluated TFF1 expression in head and neck cancer so far." (PMID 29296124, 2017).
hyperplastic polyp (1 paper, 2021). A polyp found mainly in the stomach and colon. "In hyperplastic polyps, TFF1 was detected as a diffuse cytoplasm staining in more than 75% of the cells." (PMID 34679875, 2021).
leukemia (1 paper, 2020). A malignant (clonal) hematologic disorder, involving hematopoietic stem cells and characterized by the presence of primitive or atypical myeloid or lymphoid cells in the bone marrow and the blood. "As a transcript factor, EBF1 over-expression increases DNA damage by directly targeting RAD51 in leukemia, while EBF1 knockdown promotes cell proliferation and migration by increasing CD133, Oct3/4, and TFF1 expression in CCA." (PMID 32676457, 2020).
liver fibrosis (1 paper, 2025). "In addition, we have previously reported that loss of TFF1 resulted in the increase in liver weight and the decrease in liver fibrosis after liver injury, suggesting that loss of TFF1 contributed to the regeneration of the liver probably due to the differentiation of dHPCs into hepatocytes." (PMID 40940735, 2025).
measles (1 paper, 2024). A highly contagious viral infection caused by the measles virus. "It is currently unknown whether MeV equally induces TFF1 and 3 expression in the human respiratory tract and what impact disease history of measles patients may have on severity of secondary complications." (PMID 38331906, 2024).
metastatic carcinoma (1 paper, 2009). A carcinoma which has spread from the original site of growth to another anatomic site. "In all eight cases, in which TFF1 was detected in the absence of TFIZ1, metastatic carcinoma cells had disseminated to lymph nodes." (PMID 18722547, 2009).
mucinous lung adenocarcinoma (1 paper, 2022). "In addition to enabling the development of mucinous lung adenocarcinoma, LKB1 loss is associated with increased expression of markers of gastric differentiation, such as TFF1 and MUC5AC in human and mouse lung cancer." (PMID 35228570, 2022).
mucinous ovarian cancer (1 paper, 2022). An invasive malignant neoplasm that arises from the ovary and is characterized by the presence of malignant epithelial cells that contain intracytoplasmic mucin and may resemble the epithelial cells of the endocervix or gastrointestinal tract. "TFF1 specificity in mucinous ovarian cancer was previously explored using an in silico analysis of transcriptomics data." (PMID 36818673, 2022).
nasal polyps (1 paper, 2019). "Data on TFF expression in sinonasal mucosa and nasal polyp tissue from CRSwNP are scarce, thus, the aim of this study was to assess expression levels of TFF1 and TFF3 genes in patients with CRSwNP and a control group of patients undergoing septoplasty." (PMID 31683988, 2019). "In our study, we were able to detect mRNA levels of TFF1 and TFF3 genes and proteins in all samples from both CRSwNP (nasal polyps, bulla ethmoidalis, and middle nasal turbinate) and control patients (inferior nasal turbinate)." (PMID 31683988, 2019). "TFF1 and TFF3 expression levels in sinonasal mucosa and nasal polyps were compared between the patients with positive sinus swabs and the group of patients whose swabs were sterile." (PMID 31683988, 2019). "We would like to emphasize that our study is the first to assess and analyze the expression pattern of TFF1 and TFF3 genes and peptides in a representative number of nasal polyp tissues collected from CRSwNP patients." (PMID 31683988, 2019). "Expressions of TFF1 and TFF3 were determined in specimens of middle nasal turbinate (MNT-0), bulla ethmoidalis (BE), and nasal polyps (NP) from CRSwNP patients (n = 29) and inferior nasal turbinate from a group of control patients (underwent nasal septoplasty, n = 25)." (PMID 31683988, 2019). "A recent study reported increased TFF1 gene and protein expression in patients suffering from either CRS or nasal polyposis without CRS, but did not explore TFF1 expression in the CRSwNP patients." (PMID 31683988, 2019).
nematode infection (1 paper, 2011). "The potential role of TFF3 during nematode infections has been related to mucosal defense and tissue restitution but it still remains unknown if TFF1 may also contribute to tissue repair." (PMID 21569362, 2011).
oral squamous cell carcinoma (1 paper, 2017). "In salivary gland tumors, a higher expression of TFF1, TFF2, and TFF3 was found, while in oral squamous cell carcinoma TFF2 and TFF3, but not TFF1, were downregulated with respect to healthy tissue." (PMID 29296124, 2017).
osteoarthritis (1 paper, 2019). A noninflammatory degenerative joint disease occurring chiefly in older persons, characterized by degeneration of the articular cartilage, hypertrophy of bone at the margins and changes in the synovial membrane. "Gene expression of TFF1, TFF2, and TFF3 of healthy, osteoarthritis (OA), and rheumatoid arthritis (RA) affected SM was analyzed by semi-quantitative PCR." (PMID 31817054, 2019).
ovarian tumor (1 paper, 2022). "Identification of elevated TFF1 protein levels in diverse cancers such as pancreatic, colonic, and ovarian tumor tissues indicate a universal function in tumor progression via stimulation of cell migration, survival, invasiveness, and distant spread." (PMID 36818673, 2022). "A role in tumor progression via stimulation of cell migration, survival, invasiveness, and distant spread is further supported by detection of elevated levels of TFF1 in pancreatic, colonic, and ovarian tumor tissues." (PMID 36818673, 2022).
pancreatic adenocarcinoma (1 paper, 2024). "Only recently, the de novo expression of TFF1 has been associated with gemcitabine resistance in pancreatic adenocarcinomas, and TFF1 silencing increased sensitivity to gemcitabine in vitro and in vivo." (PMID 39410561, 2024). "The extent of TFF1 staining was unrelated to histopathological parameters of malignancy in 312 gastric and 485 pancreatic adenocarcinomas." (PMID 39410561, 2024).
Parkinson disease (1 paper, 2013). A progressive degenerative disorder of the central nervous system characterized by loss of dopamine producing neurons in the substantia nigra and the presence of Lewy bodies in the substantia nigra and locus coeruleus. "In conclusion, we show for the first time that distinct subpopulations of midbrain dopaminergic neurons express TFF1, and that this expression pattern is altered in a rat model of Parkinson’s disease." (PMID 24116124, 2013). "To further verify the notion that TFF1-ir cells may represent dopaminergic projection neurons we performed immunohistochemical analyses for TFF1 in an animal model of Parkinson’s disease (PD)." (PMID 24116124, 2013). "The present study shows for the first time that trefoil factor 1 (TFF1) is markedly expressed in the developing and adult rat ventral mesencephalon, which is of particular interest in relation to Parkinson’s disease (PD)." (PMID 24116124, 2013).
Pleural effusion (1 paper, 2024). The presence of an excessive amount of fluid in the pleural cavity. "The expression pattern of FAM83A in the pleural effusion of LUAD patients was relatively consistent with that of TFF-1 and NapsinA, and even stronger in some specimens that were weakly positive or negative for TTF1/NapsinA." (PMID 38914812, 2024). "To verify our hypothesis, we analyzed the expression of FAM83A, TFF-1 and NapsinA in pleural effusion cell blocks from 40 LUAD patients to 21 non-neoplastic patients through IHC." (PMID 38914812, 2024). "The expression levels of FAM83A, TFF-1, and NapsinA in 94 paired LUAD and adjacent normal tissues, and in the pleural effusion specimens of 40 LUAD and 21 non-neoplastic patients were evaluated by immunohistochemistry." (PMID 38914812, 2024).
primary biliary cholangitis (1 paper, 2025). Primary biliary cholangitis (PBC) is a chronic and slowly progressive cholestatic liver disease of autoimmune etiology characterized by injury of the intrahepatic bile ducts that may eventually lead to liver failure. "Patients with biliary dysfunction, such as primary biliary cholangitis and sclerosing cholangitis, suffer from the inflammation and destruction of bile ducts, thus TFF1-treatment with these patients can overcome their clinical conditions." (PMID 40940735, 2025). "The ability of TFF1 to accelerate the differentiation of HPCs into BECs might be useful for treating patients with biliary-related dysfunctions, such as primary biliary cholangitis (PBC) and primary sclerosing cholangitis (PSC)." (PMID 40940735, 2025).
proctitis (1 paper, 2024). An inflammatory process affecting the anus. "TFF1’s role in epithelial repair and protection against mucosal damage could be very important in reducing the severity of gastrointestinal symptoms, such as proctitis and abdominal pain, which are commonly observed in infected patients." (PMID 39456924, 2024).
pterygium (1 paper, 2009). A wedge-shaped fibrovascular lesion arising from the bulbar conjunctiva and extending to the cornea. "Genes up-regulated in pterygium include fibronectin (FN1), CEACAM5 (CEA), CD24, SPARC, MSMB and TFF1." (PMID 19272163, 2009). "Other up-regulated proteins like small proline rich protein 1B (SPRR1B), CD24, S100 calcium binding protein, SPARC, TFF1, SPRR1B and SERPINB13 also govern the wound healing process and cornification of epithelium, again, supporting the hypothesis of aberrant wound response in pterygium." (PMID 19272163, 2009).
pulmonary fibrosis (1 paper, 2024). Chronic progressive interstitial lung disorder characterized by the replacement of the lung tissue by connective tissue, leading to progressive dyspnea, respiratory failure, or right heart failure. "To address this question, we assessed the effect of Tff1-Treg depletion on the severity of pulmonary fibrosis." (PMID 39286257, 2024). "Taken together, these results indicate that Tff1-Tregs play a protective role in preventing the exacerbation of BLM-induced pulmonary fibrosis." (PMID 39286257, 2024). "Taken together, these data suggest the relevance of Tff1-Tregs in the pathogenesis of BLM-induced pulmonary fibrosis." (PMID 39286257, 2024). "Collectively, these data suggest that lung Tregs specifically express Tff1 during BLM-induced pulmonary fibrosis." (PMID 39286257, 2024). "Collectively, our study reveals Tff1-Tregs that appear specifically in inflammatory/fibrotic lungs and their significance in suppressing pulmonary fibrosis." (PMID 39286257, 2024). "In this study, to gain a better understanding of the significance of Tregs in pulmonary fibrosis, we perform single-cell RNA-sequencing (scRNA-seq) and Bulk RNA-seq analyses, and reveal the appearance of Tregs uniquely expressing Trefoil factor 1 (Tff1) in the BLM-injured lungs." (PMID 39286257, 2024). "Therefore, to investigate the role of Tff1 in Tregs during pulmonary fibrosis, we generated Foxp3-Cre/Tff1fl/fl mice, in which Tff1 expression in Tregs was specifically disrupted." (PMID 39286257, 2024). "Thus, although the role of Tff1 in BLM-induced pulmonary fibrosis remains unclear, Tff1 itself may play a limited role." (PMID 39286257, 2024). "However, unlike in AAA, our examination using Foxp3-Cre/Tff1fl/fl mice in the BLM-induced pulmonary fibrosis model revealed that the absence of Tff1 produced by Tregs did not affect the degree of fibrosis." (PMID 39286257, 2024). "In this study, we revealed a unique subset of Tregs expressing Tff1, which are not present in healthy lungs but emerge during BLM-induced pulmonary fibrosis, contributing to the inhibition of disease progression." (PMID 39286257, 2024).
renal cell carcinoma (1 paper, 2024). "Another study in renal cell carcinomas did not suggest any relationship between TFF1 expression and parameters of cancer aggressiveness." (PMID 39410561, 2024).
renal failure (1 paper, 2015). "Interestingly, we found elevated total TFF1 urine levels with the onset of renal failure." (PMID 26390128, 2015).
ulcers (1 paper, 2022). "Some investigators have reported that transgenic mice with overexpression of human TFF1 in the jejunum had a low incidence of ulcers in the gastrointestinal tract, suggesting that TFF1 plays an important role in gastrointestinal repair and protection." (PMID 34898361, 2022).
viral infections (1 paper, 2024). "Although TFF1 is not directly linked to virion physiology, its involvement in maintaining mucosal integrity and facilitating immune defenses can indirectly influence virion dynamics, particularly in tissues susceptible to viral infections." (PMID 39456924, 2024).
tumor (137 papers, 2007 to 2026). "Our results indicate that low BC TFF1 expression is associated with younger age and aggressive tumor features, on top of serving as a predictor of the basal-like subtype." (PMID 41547953, 2026). "The PRDM family members play role in cancer suppression, while ABCG1, BACE2, and TFF1 are implicated in tumor formation in various studies." (PMID 38395755, 2024). "Recent studies suggested a potential link between TFF1 and specific clinico-pathological tumor features, suggesting its diagnostic and prognostic value as an RB biomarker." (PMID 37835522, 2023). "Summarizing, one can state that the analysis of TFF1 in the AH of RB patients opens the field for additional diagnostic approaches and therapy monitoring, using TFF1 as a potential biomarker for RB tumor cells." (PMID 37835522, 2023). "The most obvious mechanistic explanation for this loss is death of TFF1-expressing RB tumor cells in the course of therapy." (PMID 37835522, 2023). "In 24% of cases (9/38), the tumor tissue displayed a mixed staining pattern, with partial loss of TFF1 staining and some positive areas for TFF1." (PMID 36139637, 2022). "Differentially expressed genes (DEGs) between domain 4 and domain 13 includes ABCC11, ABCC12 and TFF1, in which the first two are multidrug resistance genes and the last one is associated with tumour differentiation." (PMID 36250636, 2022). "When the tumor was positive for TFF1 it was often associated with a mucinous phenotype, indicating that such tumors originated from goblet cells of the mucosa." (PMID 36139637, 2022). "Tff2 inhibition likely promotes tumor growth due to the loss of anti-proliferative gastrokine and Tff1 genes." (PMID 32231118, 2020). "Trefoil factor 1 (TFF1) expression (fold change=-2.68 in our data) exhibited inverse association with tumor size and histological grade." (PMID 30175120, 2018). "The product of TFF1 is estrogen-induced breast cancer-associated peptide, and this is indicated to be involved in breast carcinogenesis and a variety of other tumor progression mechanisms." (PMID 24959251, 2014). "In LN metastases, low TFF1 protein expression was associated with aggressive tumor features." (PMID 41547953, 2026). "Although TFF1 expression in tumor cells is associated with chemosensitivity, TFF1 is a secreted protein, and it remains unclear whether TFF1 functions intracellularly or extracellularly." (PMID 38872370, 2024). "Furthermore, we investigated if TFF1 is secreted exclusively by RB tumor cells or also by tumor-associated stromal cells." (PMID 37835522, 2023). "Thus, AH seems to be superior to blood serum as an LB for RB, not only for detecting tumor-associated chromosomal changes in whole genome sequencing, but also for TFF1 monitoring." (PMID 37835522, 2023). "The inhibiting event can be toxic, infectious, mutation of a tumor-suppressor gene in gastric progenitor cells, or deletion of a gene that is important in gastric barrier function, such as Claudin 18, or for mucosal protection, such as TFF1 or Muc5." (PMID 35426084, 2022). "Based on these findings, they speculated that the loss of TFF1 resulted in the epithelial–mesenchymal transition (EMT) of tumor cells and, therefore, upregulation of TFF1 might inhibit the EMT in cancer cells." (PMID 34679875, 2021). "Taken together with our results, the current study supports the tumor suppressive role of TFF1, where its silencing triggers loss of mucosal integrity with activation of a plethora of signaling events, including STAT3, that acts concertedly to promote tumourigenesis." (PMID 31292446, 2019). "Additionally, increased TFF1 expression in para-carcinoma tissue suggests that TFF1 is associated with tumour suppression and differentiation." (PMID 30612555, 2019). "Moreover, we assessed the possible association between tumor TFF1 expression or methylation status and the clinicopathological characteristics of ESCC patients." (PMID 29296124, 2017).